RAD51AP1 (RAD51 associated protein 1)
Description:
Structure-specific DNA-binding protein involved in DNA repair by promoting RAD51-mediated homologous recombination. Acts by stimulating D-Loop formation by RAD51: specifically enhances joint molecule formation through its structure-specific DNA interaction and its interaction with RAD51. Binds single-stranded DNA (ssDNA), double-stranded DNA (dsDNA) and secondary DNA structures, such as D-loop structures: has a strong preference for branched-DNA structures that are obligatory intermediates during joint molecule formation. Cooperates with WDR48/UAF1 to stimulate RAD51-mediated homologous recombination: both WDR48/UAF1 and RAD51AP1 have coordinated role in DNA-binding during homologous recombination and DNA repair. WDR48/UAF1 and RAD51AP1 also have a coordinated role in DNA-binding to promote USP1-mediated deubiquitination of FANCD2. Also involved in meiosis by promoting DMC1-mediated homologous meiotic recombination. Key mediator of alternative lengthening of telomeres (ALT) pathway, a homology-directed repair mechanism of telomere elongation that controls proliferation in aggressive cancers, by stimulating homologous recombination. May also bind RNA; additional evidences are however required to confirm RNA-binding in vivo.
Synonyms: PIR51
Tractability: PROTAC: UniProt records ubiquitination sites on it; ubiquitination databases record sites on it.
Gene: Protein-coding gene on chromosome 12 (4,538,798 to 4,560,254, forward strand). Ensembl gene ENSG00000111247.
Subcellular location: Chromosome; Nucleus; Chromosome, telomere
Subcellular location (Human Protein Atlas): Nucleoplasm
Pathways (Reactome):
DNA Repair: HDR through Homologous Recombination (HRR); Homologous DNA Pairing and Strand Exchange; Resolution of D-loop Structures through Holliday Junction Intermediates; Resolution of D-loop Structures through Synthesis-Dependent Strand Annealing (SDSA)
Disease: Defective HDR through Homologous Recombination Repair (HRR) due to PALB2 loss of BRCA1 binding function; Defective HDR through Homologous Recombination Repair (HRR) due to PALB2 loss of BRCA2/RAD51/RAD51C binding function; Defective homologous recombination repair (HRR) due to BRCA1 loss of function; Impaired BRCA2 binding to PALB2
Gene Ontology:
Molecular function: D-loop DNA binding; DNA binding; DNA secondary structure binding; double-stranded DNA binding; protein binding; RNA binding; single-stranded DNA binding
Biological process: cellular response to ionizing radiation; DNA damage response; double-strand break repair via homologous recombination; interstrand cross-link repair; positive regulation of double-strand break repair via homologous recombination; positive regulation of reciprocal meiotic recombination; regulation of double-strand break repair via homologous recombination; DNA repair
Cellular component: chromatin; chromosome; nucleus; protein-containing complex; nucleoplasm; chromosome, telomeric region
Genetic constraint (gnomAD): Loss-of-function variants: 11 observed, 22.74 expected, observed/expected ratio (o/e) 0.48, 90% interval 0.3 to 0.8. The upper end of that interval is the gene's LOEUF score, 0.8, which puts it in group 3 of 6, group 1 being the genes least tolerant of losing a copy. Missense variants: 255 observed, 293.1 expected, observed/expected ratio (o/e) 0.87, 90% interval 0.79 to 0.96. Synonymous variants: 85 observed, 97.93 expected, observed/expected ratio (o/e) 0.87, 90% interval 0.73 to 1.04.
Homologues: Orthologues: chimpanzee RAD51AP1 (97% identical), macaque RAD51AP1 (95% identical), rabbit RAD51AP1 (81% identical), dog RAD51AP1 (80% identical), pig RAD51AP1 (74% identical), guinea pig RAD51AP1 (72% identical), mouse Rad51ap1 (63% identical), rat Rad51ap1 (56% identical), tropical clawed frog rad51ap1 (39% identical), zebrafish rad51ap1 (34% identical). Paralogues in human: NUCKS1 (24% identical).
Diseases named in the same sentence as RAD51AP1 in open-access papers:
RAD51AP1 is named in the same sentence as 54 diseases in open-access papers, as found by Europe PMC text mining. Sharing a sentence is not in itself a finding about the gene and the disease. The quoted sentences say what the papers report.
breast carcinoma (10 papers, 2012 to 2023). "RAD51AP1 expression is increased in different breast cancer subtypes and other cancers and inversely associated with overall survival." (PMID 35652094, 2022). "Moreover, Rad51ap1 deficiency abrogates tumor growth and metastasis in a breast cancer mouse model, suggesting that the RAD51AP1 protein may be a promising target of inhibition in anti-cancer therapy." (PMID 35652094, 2022). "A number of studies have demonstrated that RAD51AP1 is overexpressed and serves as an carcinogenic role in several tumors, including ovarian cancer, lung cancer, breast cancer, as well as hepatocellular carcinoma." (PMID 36197550, 2022). "RAD51AP1 is overexpressed in breast cancer stem cells population (BCSCs) and its knockout/down reduced cancer stem cells population in breast, lung, and colon cancer mouse models and improved chemotherapy and radiotherapy." (PMID 33662042, 2021). "RAD51-associated protein 1 (RAD51AP1), which induces RAD51 activation, promotes tumor growth and chemoresistance by modulating the self-renewal of breast cancer stem cells." (PMID 34511602, 2021). "For instance, RAD51AP1, a gene that functions in double-stranded DNA repair, is also positively expressed in cervical cancer and breast cancer cell lines, cancers that exhibit high expression homogeneity with malignant ovarian carcinomas." (PMID 22452920, 2012). "Moreover, RAD51AP1 was higher in higher stages or/and grades in breast cancer." (PMID 33314567, 2021). "PRMT5 expression was moderately to strongly correlated (Pearson score ≥ 0.4) with established DDR genes such as BRCA1, BRCA2, RAD51, RAD51D, RAD51AP1, FANCA, and FANCI across 125 ovarian and breast cancer cell lines." (PMID 37861290, 2023). "To exclude that this effect was specific to HeLa cells, we generated RAD54L/RAD51AP1 single KO and DKO cells in the Hs578T breast cancer cell line and tested these cells in olaparib cell survival assays." (PMID 35652094, 2022).
ovarian carcinoma (10 papers, 2012 to 2026). A malignant neoplasm originating from the surface ovarian epithelium. "RAD51AP1 was considered a novel biomarker for ovarian cancer diagnosis, and high expression of RAD51AP1 is associated with poorer overall survival (OS) in patients with ovarian cancer." (PMID 41541703, 2026). "RAD51AP1 was reported to be associated with immune infiltration of ovarian cancer, and upregulation of RAD51AP1 accompanied by accumulated Th2 cells, but decreased CD4 + T cells and CD8 + T cells." (PMID 36197550, 2022). "However, among the overlapped DE genes, we identified upregulation of genes encoding several markers typically overexpressed in ovarian cancer: cyclin E1 (Ccne1), RAD51-associated protein 1 (Rad51ap1), osteopontin (Spp1) and its signaling receptor, Cd44." (PMID 40642792, 2025). "Mechanistically, an in vitro study using ovarian cancer cells demonstrated that RAD51AP1 promoted the progression of ovarian cancer via the TGF‐β/Smad signaling pathway." (PMID 41541703, 2026). "Apart from its involvement in ovarian cancer, in our original study, we have also shown that RAD51AP1 is overexpressed in lung cancer, and silencing RAD51AP1 in vitro inhibits cell proliferation in a human lung cancer cell line." (PMID 35207688, 2022). "Recently, our group published evidence for a novel role of RAD51AP1 in lung and ovarian cancers, with up-regulation of RAD51AP1 in patient tissue and blood samples compared to control samples at mRNA level." (PMID 35207688, 2022). "In the present study, we utilized the popular microarray and bioinformatics technologies and identified RAD51AP1 as a pivotal gene in 3 GEO data sets of 15 normal and 68 ovarian cancer samples." (PMID 33314567, 2021). "When FSTL1 and RAD51AP1 genes were silenced in ovarian cancer cells, a decrease in proliferation was noted while the Bax gene expression remained unchanged." (PMID 31338320, 2019). "Here we provide additional insight into the role of RAD51AP1 in ovarian cancer (OvCa)." (PMID 35207688, 2022). "The present study complements our previous findings on the gene expression of RAD51AP1 in lung and ovarian cancers, and provides novel insight into the protein expression of RAD51AP1 in OvCa, as well as potential signaling changes due to silencing of the RAD51AP1 gene in vitro." (PMID 35207688, 2022). "In addition, suppression of RAD51AP1 by siRNA reduced cell proliferation of ovarian cancer (OvCa) cells in vitro." (PMID 35207688, 2022). "Our analysis shows that RAD51AP1 is also up-regulated in ovarian cancers." (PMID 22452920, 2012). "Furthermore, hsa-mir-140-3p, a potential regulator of RAD51AP1 according to our anti-correlation analysis, has been previously shown to be down-regulated in ovarian cancer, a finding which we confirm." (PMID 22452920, 2012). "RAD51AP1 might accelerate the progression of ovarian cancer by the TGF-β/Smad signaling pathway." (PMID 37762324, 2023). "In a study where two ovarian cancer cell lines were used (HEY and SKOV3), silencing of RAD51AP1 significantly inhibited the cell proliferation over 3 days corroborating our initial findings in SKOV3 cells." (PMID 35207688, 2022).
lung carcinoma (6 papers, 2021 to 2022). "Overexpression of RAD51AP1 in ovarian, breast and lung cancer has been generally associated with poorer overall survival." (PMID 35207688, 2022). "Further studies indicates that overexpression of RAD51AP1 promotes the proliferation of lung cancer cells and correlates to poor prognosis." (PMID 34721973, 2021). "To exclude that this effect was specific to HeLa cells, we depleted RAD51AP1 and/or RAD54L in A549 lung cancer cells." (PMID 35652094, 2022). "Unlike the general genome stability function of RAD51AP1, it also presents oncogene-like functions in breast, ovarian, and lung cancers as highly expressed in tumor tissues and correlated with poor prognosis." (PMID 36468013, 2022).
cervical cancer (5 papers, 2012 to 2025). A primary or metastatic malignant neoplasm involving the cervix. "JQ1 (a BRD4 inhibitor) sensitized cervical cancer to radiation therapy by suppressing RAD51AP1 transcription." (PMID 37914994, 2023). "Inhibition of BRD4 reduces RAD51AP1 transcription and sensitizes cervical cancer to radiation." (PMID 37035213, 2023). "We can still identify some genes related to cervical cancer progression from the samples of the two patients after treatment, including ATF3, GPX3, IL10, IL6, RAD51AP1, MGMT, WWOX." (PMID 37914994, 2023).
glioma (4 papers, 2019 to 2023). A benign or malignant brain and spinal cord tumor that arises from glial cells (astrocytes, oligodendrocytes, ependymal cells). "Altogether, these results demonstrated that RAD51AP1 is an oncogene in glioma and is highly associated with EGFRvIII." (PMID 31532757, 2019). "We previously reported that RAD51AP1 is correlated with glioma clinical grades and has an oncogenic role in GBM32." (PMID 37283490, 2023). "Overexpression of RAD51AP1 had a minimal impact on the chemoresistance of glioma cells; however, knockdown of this gene significantly increased the degree of DNA damage." (PMID 37283490, 2023). "To the best of our knowledge, we herein identify RAD51AP1 as an oncogene in glioma for the first time." (PMID 31532757, 2019). "Bioinformatic analyses revealed that RAD51AP1 is significantly enriched in high-grade gliomas in the CGGA, TCGA and GSE16011 datasets." (PMID 31532757, 2019). "Kaplan-Meier survival analysis confirmed the poor outcomes of patients with both low- and high-grade gliomas expressing high levels of RAD51AP1." (PMID 31532757, 2019). "Collectively, our microfluidic-based scRNA-seq driven by a single genetic event revealed a previously unappreciated implication of EGFRvIII in the heterogeneity of GBM and identified RAD51AP1 as an oncogene in glioma." (PMID 31532757, 2019). "Overall, these data indicated that RAD51AP1 facilitated DSB repair in MGMT-methylated glioma cells and could be a therapeutic target in this type of glioma." (PMID 37283490, 2023). "Knockdown of RAD51AP1 enhanced the sensitivity of TMZ; however, overexpression of RAD51AP1 was not sufficient to cause chemotherapy resistance in glioma cells." (PMID 37283490, 2023). "RAD51AP1 is a necessary mediator of E2F1 for glioma chemoresistance." (PMID 37283490, 2023). "Although reported in ovarian cancer, lung cancer and melanoma, RAD51AP1 is still a rarely studied protein, and its role in glioma is unknown." (PMID 31532757, 2019). "Further analysis of RAD51AP1 revealed that it is an independent prognostic factor of glioma." (PMID 31532757, 2019). "Therefore, our study reveals the impact of EGFRvIII on the dynamic alterations of glioma cells at single-cell resolution, further elucidating the exact mechanism of EGFRvIII in glioma and identifying the role of RAD51AP1 in GBM." (PMID 31532757, 2019). "In this study, we collected intact expression data of RAD51AP1 from the public database, and verified it was significantly over-expressed in 33 cancer types and correlated with poor prognosis in 13 cancer types, including glioma, adrenocortical carcinoma, lung adenocarcinoma." (PMID 36468013, 2022). "We constructed an intracranial glioma model with TBD0220 cells to further test and verify the role of RAD51AP1 in TMZ resistance in vivo." (PMID 37283490, 2023). "Because E2F1 was regulated by TMZ and DP1 was minimally impacted by this treatment, we concluded that E2F1 has a key role in RAD51AP1 regulation, as least in TMZ-resistant glioma cells." (PMID 37283490, 2023). "We further demonstrated that RAD51AP1 is a mediator of E2F1 in TMZ resistance and that targeting RAD51AP1 has great potential in sensitizing glioma cells to TMZ." (PMID 37283490, 2023). "We analyzed the survival rate of glioma patients in the CGGA database and found that RAD51AP1 is a better prognostic factor in MGMT-methylated patients." (PMID 37283490, 2023). "While RAD51AP1 is known to promote RAD51-mediated homologous recombination, the role of RAD51AP1 in glioma has rarely been studied." (PMID 31532757, 2019). "Furthermore, we showed that RAD51AP1 was a GBM oncogene by bioinformatics analysis, generated an intracranial mouse glioma model and performed clinical multiple spot samplings." (PMID 31532757, 2019).
colorectal cancer (3 papers, 2021 to 2023). A primary or metastatic malignant neoplasm that affects the colon or rectum. "For example, in colorectal cancer, it can act as a sensitizer to chemotherapy, and Rad51ap1-deficient mice were found to be protected against CRC." (PMID 35207688, 2022).
esophageal cancer (3 papers, 2022 to 2025). A primary or metastatic malignant neoplasm involving the esophagus. "KIF4A-based multi-gene signatures, such as KIF4A + RAD51AP1 + CDKN3 in oesophageal cancer, are poised to enter clinical practice as routine tools for molecular diagnostics and prognostic predictions, enabling more precise patient stratification." (PMID 41361459, 2025). "The survival analysis showed that the expression of RAD51AP1 was significantly correlated with the prognosis of esophageal cancer." (PMID 36197550, 2022).
esophageal squamous cell carcinoma (3 papers, 2020 to 2023). Esophageal squamous cell carcinoma (ESCC) is a type of esophageal carcinoma (EC) that can affect any part of the esophagus, but is usually located in the upper or middle third. "KIF20A and RAD51AP1 were more informative biomarkers of esophageal squamous cell carcinoma." (PMID 32963620, 2020). "RAD51AP1 silencing significantly inhibited cell proliferation and invasion in esophageal squamous cell carcinoma (ESCC), thereby highlighting its potential as a novel target for ESCC treatment." (PMID 37762324, 2023).
melanoma (3 papers, 2017 to 2020). A malignant, usually aggressive tumor composed of atypical, neoplastic melanocytes. "Further, we identified 110 CD271-responsive genes predominantly expressed in melanoma metastases, among them were NEK2, TOP2A and RAD51AP1 as potential drivers of melanoma metastasis." (PMID 28112719, 2017). "In malignant melanoma, high expression levels of RAD51AP1 may be an important molecular event involved in tumor invasion and metastasis." (PMID 32963620, 2020). "RAD51AP1 was identified as a potential driver of melanoma metastasis." (PMID 29697361, 2018). "High expression of metastasis-associated CD271-responsive genes NEK2, RAD51AP1, TOP2A and NGF in drug-resistant MeWo cells and their drug-dependent regulation, may have consequences for the priming of melanoma cells for metastasis." (PMID 28112719, 2017).
non-small cell lung carcinoma (3 papers, 2020 to 2022). A group of at least three distinct histological types of lung cancer, including non-small cell squamous cell carcinoma, adenocarcinoma, and large cell carcinoma. "A recent study found that RAD51AP1 is highly expressed in non-small cell lung cancer patients and facilitates invasion and metastasis by inducing epithelial-mesenchymal transitions." (PMID 33488669, 2020).
prostate carcinoma (3 papers, 2020 to 2024). A carcinoma that arises from epithelial cells of the prostate gland. "Additionally, DNA methylation in the RAD51AP1 promoter region may be associated with prostate carcinoma." (PMID 32963620, 2020). "Next, SNVs in DNA repair genes (RAD51-associated protein 1 [RAD51 AP1], structural maintenance of chromosomes 1A [SMC1A], and activating signal cointegrator 1 complex subunit 3 [ASCC3]) were observed only in the RR prostate cancer cells." (PMID 39719436, 2024).
cholangiocarcinoma (2 papers, 2022). A carcinoma that arises from the intrahepatic biliary tree (intrahepatic cholangiocarcinoma) or from the junction, or adjacent to the junction, of the right and left hepatic ducts (hilar cholangiocarcinoma). "Overexpression of RAD51AP1 has been described in other cancers, notably cholangiocarcinoma, hepatocellular carcinomas and acute myeloid leukemia with complex karyotypic abnormalities." (PMID 35207688, 2022). "Furthermore, inhibition of RAD51AP1 by short interfering RNA resulted in the cell growth suppression of cholangiocarcinoma." (PMID 36197550, 2022).
Fanconi anemia (2 papers, 2013 to 2019). Fanconi anemia (FA) is a hereditary DNA repair disorder characterized by progressive pancytopenia with bone marrow failure, variable congenital malformations and predisposition to develop hematological or solid tumors.
glioblastoma (2 papers, 2019 to 2022). The most malignant astrocytic tumor (WHO grade IV). "Thirty-three of 34 cancer types presented RAD51AP1 significantly up-regulated in tumor samples, including glioblastoma multiforme (GBM), brain lower grade glioma (LGG), uterine corpus endometrial carcinoma (UCEC), breast invasive carcinoma (BRCA), and lung adenocarcinoma (LUAD)." (PMID 36468013, 2022).
intrahepatic cholangiocarcinoma (2 papers, 2020 to 2022). A carcinoma that arises from the intrahepatic bile duct epithelium in any site of the intrahepatic biliary tree. "RAD51AP1 was a key protein in homologous recombination, and its up-regulation in intrahepatic cholangiocarcinoma and lymphoma could promote the development of cancer." (PMID 33160391, 2020). "Similarly, RAD51AP1 is up-regulated in intrahepatic cholangiocarcinoma (ICC) and knockdown of the gene resulted in suppression of cell proliferation." (PMID 35207688, 2022).